SLC13A5 (solute carrier family 13 member 5)
Diseases named in the same sentence as SLC13A5 in open-access papers (continued):
Sharing a sentence is not in itself a finding about the gene and the disease.
Obesity (17 papers, 2013 to 2025). Accumulation of substantial excess body fat. "Human hepatic SLC13A5 expression is positively associated with measures of obesity, body fat and liver fat content assessed from histology." (PMID 35323687, 2022). "The perturbation of SLC13A5 expression and/or activity is associated with non-alcoholic fatty liver disease, obesity, insulin resistance, cell proliferation, and early infantile epileptic encephalopathy." (PMID 34677420, 2021). "The alteration of the SLC13A5 expression and function in these tissues is closely associated with obesity, type 2 diabetes, non-alcoholic fatty liver disease (NAFLD), inflammation, cancer, and neurological disorders." (PMID 34677420, 2021). "The sodium-dependent citric acid transporter NaCT, which is encoded by SLC13A5, could be a promising target for interventions aimed at combating obesity." (PMID 39121110, 2024). "In addition, SLC13A5/INDY expression is strongly associated with obesity, insulin resistance, and fatty liver in humans." (PMID 35409012, 2022). "The loss of Slc13a5 also protects mice from high-fat diet induced obesity and insulin resistance." (PMID 25797421, 2015). "The researchers verified that siRNA silencing of Slc13a5 or knockout of Slc13a5 in the liver of mice can improve obesity, insulin resistance, and liver steatosis induced by a high-fat diet." (PMID 39850557, 2024). "Elevated expression of SLC13A5 has been observed from liver samples of obesity, type 2 diabetes, and non-alcoholic fatty liver disease." (PMID 34943889, 2021). "An increased expression of SLC13A5 in the liver has been observed in patients with obesity, NAFLD, and type 2 diabetes as well as in cultured primary hepatocytes treated with glucagon, BaP, or RIF." (PMID 34677420, 2021). "It is known that IL-6 levels are increased in obesity, type 2 diabetes, NAFLD, and several metabolic states that are associated with an elevated SLC13A5 expression." (PMID 34677420, 2021). "A study suggests that Slc13a5 expression is required for development of diet- and aging-induced obesity." (PMID 34659115, 2021). "Considering the important role of INDY (SLC13A5) in metabolism, INDY has become a particularly attractive target for the treatment of conditions such as obesity, diabetes, and cardiovascular diseases." (PMID 35822025, 2021). "SLC13A5 knockout (−/−) mice were protected from high-fat diet (HFD)-induced obesity, a fatty liver, and insulin resistance." (PMID 34677420, 2021). "Together with computational biology, the development of drugs targeting the SLC13A5 could be accelerated for potential therapeutics of carbohydrate and lipid metabolism disorders like diabetes, non-alcoholic fatty liver and obesity." (PMID 25797421, 2015). "Hence, SLC13A5 may serve as a potential therapeutic target in the treatment of metabolic disorders including non-alcoholic fatty liver disease, obesity and diabetes." (PMID 25797421, 2015). "A previous study observed that in liver samples from patients with obesity with insulin resistance and NAFLD, the mRNA expression of SLC13A5 was significantly increased, and was correlated with hepatic steatosis." (PMID 36844876, 2023). "Slc13a5 gene inactivation were protected the knockout mice from high-fat diet (HFD)- and aging-induced obesity, hepatic steatosis, and insulin resistance." (PMID 34659115, 2021). "Despite lack of direct links to aging, SLC13A5-/- mice (akin to pho87Δ yeast) are known to display resistance to diet and age-induced obesity, increased energy consumption, improved glucose tolerance, and increased hepatic lipid oxidation." (PMID 38012152, 2023). "Increased expression of SLC13A5 in the liver has been reported in patients with obesity, non-alcoholic fatty liver disease, and type 2 diabetes." (PMID 34943889, 2021).
Insulin resistance (13 papers, 2012 to 2025). Increased resistance towards insulin, that is, diminished effectiveness of insulin in reducing blood glucose levels. "Knockout of gene SLC13A5, encoding for a sodium-coupled plasma membrane citrate transporter, protects mice from adiposity and insulin resistance." (PMID 22300499, 2012). "Similarly, deletion of the mammalian homolog, mIndy (Slc13a5), encoding for a plasma membrane tricarboxylate transporter, protects from aging- and diet-induced adiposity and insulin resistance in mice." (PMID 26647160, 2015). "Our laboratory has demonstrated that deletion of the mIndy gene (Slc13a5) protects mice from aging and high fat diet-induced adiposity, insulin resistance and hepatic steatosis." (PMID 26647160, 2015). "Moreover, the deletion of Slc13a5 has been shown to have protective effects against high-fat diet-induced insulin resistance and has attenuated hepatic gluconeogenesis and lipogenesis." (PMID 38392976, 2024). "In mammals, deletion of the homolog of Indy (mIndy, Slc13A5), protects mice from high fat diet and aging induced obesity, insulin resistance and nonalcoholic fatty liver disease (NAFLD), at least in part through the activation of the intracellular energy sensor AMP-activated protein kinase A (AMPK)." (PMID 26318988, 2015).
type 2 diabetes (9 papers, 2013 to 2025). "Hepatic uptake of citrate from the circulation by SLC13A5 has, for instance, been implied in development of type 2 diabetes." (PMID 32639996, 2020). "Furthermore, the SLC13A5/Mindy knockout mouse showed resistance to Type 2 diabetes, displayed lower blood pressure and a lower heart rate and, under certain circumstances, increased bone elasticity and strength." (PMID 40535023, 2025). "The expression of Slc13a5 was also increased in the model of type-2-diabetes rats." (PMID 37233635, 2023).
developmental delay (8 papers, 2017 to 2025). "Here, in this study, we investigate pathogenic homozygous variants of SLC13A5 (including a novel splice site variant), causing mainly neonatal seizures and developmental delay in six patients from three different Saudi families." (PMID 36923948, 2022). "The earliest study identified SLC13A5 variants as the disease-causing variants that reported overlapping clinical features such as early-onset seizures, which appeared within any day of the first week of life, with severe developmental delay." (PMID 36923948, 2022). "Patients born before 2014, when SLC13A5 Citrate Transporter Disorder was first identified, often lacked a conclusive diagnosis for the etiology of their neonatal seizures and developmental delay." (PMID 34822404, 2021). "As SLC13A5 Citrate Transporter Disorder patients age, they experience increasingly severe motor and cognitive delays, along with ongoing seizures." (PMID 34822404, 2021). "In our study, we identified a novel nonstop mutation in the SLC13A5 gene in a Chinese family affected by infant epilepsy and developmental delay." (PMID 40313595, 2025).
fatty liver disease (8 papers, 2015 to 2024). A reversible condition wherein large vacuoles of triglyceride fat accumulate in liver cells via the process of steatosis. "Mammalian INDY (mINDY, NaCT, gene symbol SLC13A5) is a potential target for the treatment of metabolically associated fatty liver disease (MAFLD)." (PMID 36005604, 2022).
non-alcoholic fatty liver disease (7 papers, 2013 to 2025). "The SLC13A5/sodium-coupled citrate transporter is associated with the pathogenesis of T2D and non-alcoholic fatty liver disease (NAFLD)." (PMID 41425581, 2025). "SLC13A5 plays a crucial role in metabolic disorders, such as obesity, insulin resistance, and non-alcoholic fatty liver disease (NAFLD)." (PMID 41425581, 2025).
Hepatic steatosis (6 papers, 2015 to 2024). Steatosis is a term used to denote lipid accumulation within hepatocytes. "RNAi-mediated suppression of Slc13a5 expression in mice also prevents diet-induced alcoholic fatty liver." (PMID 34677384, 2021).
metabolic syndrome (6 papers, 2017 to 2025). A cluster of metabolic risk factors for CARDIOVASCULAR DISEASES and TYPE 2 DIABETES MELLITUS. "Furthermore, the importance of citrate transport deficiency extends beyond patients with SLC13A5 Citrate Transporter Disorder, due to interest in developing liver specific NaCT inhibitors to treat metabolic syndrome and extending the lifespan." (PMID 34822404, 2021). "The solute carrier family 13 member 5 (SLC13A5), a sodium-coupled citrate transporter, plays an important role in intracellular citrate homeostasis that is associated with a number of metabolic syndromes and neurological disorders." (PMID 34943889, 2021). "Moreover, several of the loci implicated in our analysis, such as those near SLC13A5, RABEP1, and WSCD1, overlap functionally with pathways previously associated with adiposity, dyslipidemia, and glucose regulation." (PMID 40429953, 2025). "Slc13a5-knockout mice have been generated; these mice do not have any overt phenotype but are resistant to experimentally induced metabolic syndrome." (PMID 28264506, 2017).
diabetes (5 papers, 2015 to 2021). "As the glucagon/insulin ratio in terms of biological activity is increased in uncontrolled type 2 diabetes, the glucagon-dependent induction of SLC13A5 expression in liver cells might contribute to hyperlipidemia associated with diabetes." (PMID 28264506, 2017). "While these data support SLC13A5 as another factor that attributes to metformin’s therapeutic effect on diabetes, alteration of SLC13A5 in the liver versus in the central nervous system may elicit opposite clinical benefits." (PMID 34943889, 2021).
early infantile epileptic encephalopathy-25 (5 papers, 2021 to 2022). "Indeed, a recent case report suggests administration of metformin in a patient with SLC13A5-associated early infantile epileptic encephalopathy-25 (EIEE-25) may increase the psychiatric episodes, while discontinuation of metformin revealed improved clinical manifestation." (PMID 34943889, 2021).
hepatoma (5 papers, 2020 to 2024). "SLC13A5, a sodium-coupled citrate transporter, plays a crucial role in hepatic energy homeostasis and hepatoma cell proliferation." (PMID 38534987, 2024). "The role of NaCT (SLC13A5) in supplying extracellular citrate has been documented at least in hepatocellular carcinoma and liver cancer cells; this process is essential for the growth and proliferation of liver cancer cells in vitro and in vivo." (PMID 33425906, 2020). "This is supported by a recent study in which SLC13A5 was shown to be a tumor promoter in hepatocellular carcinoma." (PMID 33425906, 2020). "We have shown that SLC13A5 delivers extracellular citrate into the liver carcinoma cell line HepG2 for subsequent lipid synthesis." (PMID 33425906, 2020). "In mice, knockout of a DASS family member (NaCT, SLC13A5 in humans) leads to protection against adiposity and insulin resistance, and knockout of the equivalent transporter in human hepatocarcinoma cells substantially reduces hepatoma cell proliferation and colony formation." (PMID 33087444, 2020).
amelogenesis imperfecta (4 papers, 2021 to 2025). Amelogenesis imperfecta (AI) represents a group of developmental conditions affecting the structure and clinical appearance of the enamel of all or nearly all the teeth in a more or less equal manner, and which may be associated with morphologic or biochemical changes elsewhere in the body. "Biallelic loss-of-function variants in the SLC13A5 (solute carrier family 13, member 5) gene are responsible for autosomal recessive developmental and epileptic encephalopathy 25 with amelogenesis imperfecta (DEE25)." (PMID 40313595, 2025). "Biallelic mutations in SLC13A5 cause one such disorder called as “developmental and epileptic encephalopathy 25 with amelogenesis imperfecta” (DEE25; phenotype MIM: 615905)." (PMID 36923948, 2022). "Amelogenesis imperfecta is also present in humans with biallelic loss of function variants in Slc13a5." (PMID 34069814, 2021).
liver cancer (4 papers, 2020 to 2022). An epithelial or non-epithelial malignant neoplasm that arises from the liver. "SLC13A5/NaCT, a plasma membrane citrate transporter, has recently been identified as a metabolic target in human liver cancer cell lines." (PMID 35884416, 2022). "Accordingly, when SLC13A5 is silenced in liver cancer cells, it suppresses the growth of these cells into tumors in vivo in mouse xenografts." (PMID 34677384, 2021). "Therefore, we examined the effect of DIDS on the transport function of human INDY SLC13A5 in the human liver cancer cell line HepG2." (PMID 34677384, 2021). "Therefore, SLC13A5 as the major plasma membrane transporter to bring extracellular citrate into the cytoplasm has relevance to liver cancer." (PMID 34677384, 2021). "However, whether any of these functions of β-hydroxybutyrate contributes to the suppression of liver cancer upon SLC13A5 knockdown remains to be determined." (PMID 34677384, 2021). "Interestingly, proteomic analysis of the liver cancer cell line HepG2 with and without SLC13A5 knockdown has shown evidence of increased ketogenesis in the knockdown cells with elevated levels of the ketone body β-hydroxybutyrate." (PMID 34677384, 2021).
steatosis (4 papers, 2020 to 2025). Increased lipid within the cytoplasm of cells. "Animal models have shown that the overexpression of SLC13A5 in hepatocytes leads to lipid accumulation, while its inhibition confers protection against steatosis." (PMID 40429953, 2025).
Encephalopathy (3 papers, 2017 to 2022). Encephalopathy is a term that means brain disease, damage, or malfunction. "Though biallelic variants in SLC13A5 are known to cause severe encephalopathy, the mechanism of this disease is poorly understood." (PMID 35448538, 2022).
glioblastoma (3 papers, 2010 to 2021). The most malignant astrocytic tumor (WHO grade IV). "SLC13A5 is differentially methylated between glioblastoma and normal brain tissue, as shown by whole-genome integrative analysis." (PMID 25289081, 2014).
Intellectual disability (3 papers, 2022 to 2025). "Another common feature of SLC13A5 citrate transporter disorder is intellectual disability." (PMID 37025451, 2023).
microcephaly (3 papers, 2017 to 2025). A congenital or acquired developmental disorder in which the circumference of the head is smaller than normal for the person's age and sex. "Microcephaly is reported in ~ 10% of SLC13A5 individuals, indicating that brain size reduction, possibly due to cell death as we report here, is present but is less penetrant in humans." (PMID 40208862, 2025).
osteoporosis (3 papers, 2023 to 2025). A condition of reduced bone mass, with decreased cortical thickness and a decrease in the number and size of the trabeculae of cancellous bone (but normal chemical composition), resulting in increased fracture incidence. "In contrast, for genetically predicted SLC13A5 inhibition a significant lower risk of osteoporosis emerged both for diagnosed (−0.0016; 95% CI −0.0021 to −0.0011; p = 2.3 × 10−3) and for self-reported cases (−0.0034; 95% CI −0.0047 to −0.0021; p = 9.7 × 10−3)." (PMID 38132868, 2023). "New Mendelian randomization analysis using UK Biobank data indicated that SNPs linked to reduced SLC13A5 function lowered osteoporosis risk." (PMID 38132868, 2023). "Using drug target MR, we showed that genetically proxied SLC13A5 inhibition is associated with a lower risk of both clinically diagnosed and self-reported osteoporosis in UK Biobank participants." (PMID 38132868, 2023). "However, more recent human Mendelian randomization analysis using UK Biobank data indicated that SNPs linked to reduced SLC13A5/INDY/Mindy function lowered osteoporosis risk and also predicted improved kidney function." (PMID 40535023, 2025). "The protective effects of altered SLC13A5 for osteoporosis proxied by genetic variants (SNPs) appear to contradict to previously published findings in Slc13a5-deficient mice which showed reduced bone mineral density and impaired bone mineralization leading to more fragile bones." (PMID 38132868, 2023). "Overall, based on the presented data, pharmacological inhibition of SLC13A5 function may be considered as a promising new approach to treat osteoporosis." (PMID 38132868, 2023). "Overall, our data suggest that pharmacological SLC13A5 inhibition could have utility in preventing or treating osteoporosis." (PMID 38132868, 2023). "Follow up studies with inducible Slc13a5 knockouts at an older age or administration of the SLC13A5 inhibitor in osteoporotic mice will provide further valuable insights into the beneficial effects of and mechanisms behind SLC13A5 inhibition in osteoporosis management." (PMID 38132868, 2023). "The study suggests that reduced SLC13A5 function may attenuate age-related bone fragility and underscores the potential of pharmacological inhibition of SLC13A5 as an approach for the treatment of osteoporosis." (PMID 38132868, 2023). "As SLC13A5 inhibitors are under development for fatty liver and NASH, synergies may be possible for patients with metabolic diseases and osteoporosis co-morbidity." (PMID 38132868, 2023). "Osteoblasts take up citrate from circulation through SLC13A5 but can also produce their own citrate for bone formation in the TCA, and several dietary supplement studies showed the beneficial effects of a citrate supplementation diet on osteoporosis." (PMID 38132868, 2023).
progeria (3 papers, 2023 to 2025). "In essence, the ATases appear to be the last output of the SLC13A5/AT-1 metabolic network that is intimately linked to a segmental form of progeria." (PMID 40930841, 2025). "In line herewith, another recent publication showed that increased expression of Slc13a5 caused a progeria-like phenotype in both male and female mice with reduced bone density." (PMID 38132868, 2023). "Both animals displayed increased cytosolic levels of citrate and acetyl-CoA; however, SLC13A5 sTg mice developed a progeria-like phenotype with premature death, while SLC25A1 sTg mice did not." (PMID 37689798, 2023). "Therefore, defective proteostasis within the ER and secretory pathway is likely to play an important mechanistic role in the SLC13A5 sTg progeria phenotype." (PMID 37689798, 2023). "Finally, our results indicate that SLC13A5-derived citrate is tightly linked to ER proteostasis and associated progeria, while SLC25A1-derived citrate is not." (PMID 37689798, 2023).
abscesses (1 paper, 2017). "Some Slc13a5-/- mice had discrete mandibular swellings which correlated with tooth and mandibular abscesses in 13-week-old mice." (PMID 28406943, 2017).
age (1 paper, 2023). A temporal measurement of the time period elapsed since an identifiable point in the life cycle of an organism. "Reduced expression of the plasma membrane citrate transporter SLC13A5, also known as INDY, has been linked to increased longevity and mitigated age-related cardiovascular and metabolic diseases." (PMID 38132868, 2023).
Arthritis (1 paper, 2025). Inflammation of a joint. "The RO/E index indicated that the osteoblasts_Gapd2 subpopulation (0.70) was negatively associated with arthritis and spondylitis, whereas osteoblasts_Slc13a5 (1.91) showed a positive correlation (p < 0.05)." (PMID 41459160, 2025).
Ataxia (1 paper, 2022). Ataxia refers to impaired coordination of voluntary muscle movement. "Further, neuronal membrane integrity and altered signaling due to a lack of sphingolipids and glycerophospholipids could be plausible mechanisms to explain ataxia and neurodevelopmental delays in children with SLC13A5 deficiency." (PMID 35448538, 2022).
cortical dysplasia (1 paper, 2022). "For example, a brother and sister carrying the same compound heterozygous variants of SLC13A5 presented with varying intractable seizures and focal brain lesions; one of the patients had focal cortical dysplasia and was more developmentally delayed than the other sibling." (PMID 36923948, 2022).